IL5 (interleukin 5)
Diseases named in the same sentence as IL5 in open-access papers (continued):
Sharing a sentence is not in itself a finding about the gene and the disease.
cyst (6 papers, 2014 to 2024). A sac-like closed membranous structure that may be empty or contain fluid or amorphous material. "Compared with BALB/c mice, FVB mice is a more favorable host for C. sinensis on the basis of cyst formation in bile ducts because they have increased production of Th2-associated anti-inflammatory cytokines, including IL-4, IL-5, IL-13, IL-10 and TGF-β." (PMID 28784165, 2017). "Despite similar cytokine levels between these groups, HIV- participants with cysticercosis exhibited significantly depressed levels of IL-5, suggestive of a diminished eosinophil response critical for cyst clearance." (PMID 39093864, 2024). "But during cyst establishment and growth, there is a switch to a Th2 response by secreted IL-4, IL-5, IL-6, IL-10 and so on, which is beneficial to parasite survival." (PMID 35360110, 2022). "However, once the cyst infects the CNS, even asymptomatic individuals show a predominantly Th2-skewed response, characterized by elevated levels of IL-4, IL-5, IL-13, and IgG." (PMID 39093864, 2024). "Together with the overproduction of IL-4, IL-5, and IL-13, these cytokines may mount a response that could destroy the T. saginata PO form and prevents development of the cyst in vivo." (PMID 30870421, 2019).
cystic fibrosis (6 papers, 2009 to 2022). Autosomal recessive disorder caused by pathogenic variants in the CFTR gene (cystic fibrosis transmembrane conductance regulator), which encodes a chloride and bicarbonate channel expressed in epithelial cells, and follow the diagnosis criteria. "We showed here that instillation of “sterile” agarose beads in a rat biofilm model, extensively used in the field of cystic fibrosis research, activates the same Th2 cytokines (IL-5 and IL-13) and Th2 innate cells (eosinophils and Arg1+ M2 macrophages) as observed in human CF patients." (PMID 28680858, 2017). "In addition, estrogen has been shown to aggravates inflammation in pseudomonas aeruginosa pneumonia in cystic fibrosis mice via increasing the total white blood cell counts and neutrophils, Th1 cytokines (TNF-α and IL-6) Th2 cytokines (IL-5) and extaxin." (PMID 22563373, 2012).
DRESS syndrome (6 papers, 2019 to 2025). "This case demonstrates the effective use of anti-IL-5 therapy in managing severe, corticosteroid-refractory DRESS syndrome with fulminant liver failure, thereby avoiding the need for an imminent liver transplant." (PMID 40726873, 2025). "Interleukin (IL)-17 is overexpressed in DRESS syndrome, including IL-17E, which can further raise circulating eosinophils, eotaxin, IL-4 level, IL-5 level, and IgE, thereby enhancing the eosinophilic immune response." (PMID 36059007, 2022). "Eosinophilic activation as well as activation of the inflammatory cascade in DRESS syndrome may be induced by interleukin-5 release from drug-specific T-cells." (PMID 31308976, 2019).
emphysema (6 papers, 2013 to 2024). "CD8+ T-cells primarily secrete IL-4 and IL-5 cytokines, both of which are implicated in lung parenchymal tissue damage that exacerbates the development of emphysema." (PMID 35350787, 2022). "Elastic fibers were elevated in the lung alveolar walls after blocking IL-5 compared to the emphysema group receiving control antibodies." (PMID 37816708, 2023). "Depletion of eosinophils through the use of anti-interleukin-5 antibodies ameliorated elastase-induced emphysema." (PMID 37816708, 2023). "The bronchoalveolar lavage (BAL) interleukin 13 (IL‐13), IL‐4, and IL‐5 levels in the overlap model were higher than in the pulmonary emphysema model and lower than in the type 2 airway inflammation model, but IL‐33 level in the lung was higher than in other models." (PMID 38652015, 2024). "Eosinophils were depleted through IL-5 blockade to uncover whether they were indispensable for PPE-induced emphysema." (PMID 37816708, 2023). "Previously, we showed that constitutive overproduction of mature IL-18 protein in the lungs of B6 background transgenic mice resulted in the increased production of IFN-γ IL-5, and IL-13, and severe emphysema accompanied by pulmonary inflammation, especially by CD8+ T cells." (PMID 23382928, 2013). "Compared to the emphysema model (ELA), the ACO group was superior in expressing of IL-1β, IL-4, IL-5, IL-6, IL-13, and IFN-γ." (PMID 37511021, 2023).
encephalitis (6 papers, 2017 to 2025). An acute inflammatory process affecting the brain parenchyma. "In experimental models, Th2 cytokines (IL-2, IL-4, IL-5, and IL-10) protected JEV-infected mice against viral encephalitis, and high CSF IL-10 levels were associated with protection against brain damage." (PMID 33776990, 2021). "IL-5 levels in the sera of EV71 patients with encephalitis have been demonstrated to be an accurate prognostic marker of death." (PMID 29156632, 2017).
fibrosarcoma (6 papers, 1993 to 2023). A malignant mesenchymal fibroblastic neoplasm affecting the soft tissue and bone. "IL5 has been linked with anti-tumor activities, specifically, tumor immune surveillance by eosinophils as demonstrated in lung and fibrosarcoma mice models." (PMID 24473087, 2014). "Th2 cells contribute to fibrosarcoma and lung tumor progression by secreting IL-4, IL-5, IL-10, IL-13, and IL-17 and promoting the recruitment of M2 macrophages and eosinophils via the expression of IL-5 and IL-13." (PMID 37568713, 2023). "Indeed, IL-5 transgenic mice expressing high endogenous levels of eosinophils displayed resistance to the development of methylcholanthrene (MCA)-induced fibrosarcomas." (PMID 31730503, 2019). "Here we demonstrate that the weakly immunogenic murine fibrosarcoma FS29 had reduced growth rate and in some cases was rejected by syngeneic animals, when modified to secrete either IL-2 or IL-4, but not IL-5." (PMID 8347485, 1993).
Hepatitis (6 papers, 2016 to 2024). Inflammation of the liver. "IL-5 is also associated with increasedliver injury in hepatic disease models, including LPS-induced hepatotoxicity andconcanavalin A (ConA)-induced hepatitis." (PMID 27812602, 2016). "IL-5 is a Th2 cytokine that has been confirmed to be associated with increased liver injury in hepatitis induced by lipopolysaccharide and concanavalin A. Only a few articles reported that APAP increases IL-5 expression in mouse liver." (PMID 36414987, 2022). "IL-5 was shown to be involved in the maturation and differentiation of eosinophils, and IL-15 can ameliorate hepatitis by inhibiting cytokine production (including IL-4 and IL-5) to reduce the infiltration of hepatic eosinophils." (PMID 33506011, 2021). "Furthermore, IL-5 promotes hepatic necrosis in the ConA-induced Tcell-mediated hepatitis murine model." (PMID 27812602, 2016). "TFA-JHDN-5 immunizations induced significantly more hepatitis, serum levels of TFA antibodies, CYP2E1 autoantibodies, and hepatic tissue levels of interleukin (IL)-1β, IL-2, IL-4, IL-5, IL-6, IL-17, interferon (IFN)-γ, and tumor necrosis factor (TNF)-α by 3 weeks." (PMID 30305319, 2018).
hepatocellular carcinoma (6 papers, 2018 to 2025). A malignant tumor that arises from hepatocytes. "Significantly high levels of cytokines, interleukin-5 (IL-5) and interleukin-6 (IL-6), were reported in the patients diagnosed with hepatocellular carcinoma compared to the healthy patients." (PMID 39408564, 2024). "In mice bearing hepatocellular carcinoma, interleukin 5 (IL-5) activates eosinophils, leading to suppression of tumor growth." (PMID 34359674, 2021). "On the other hand, a report on eotaxin-expressing hepatocellular carcinoma showed in vivo eosinophil recruitment into tumors and infrequent tumor progression in IL-5 transgenic mice." (PMID 30477171, 2018). "Lan T also reported that in hepatocellular carcinoma KIAA1429 controls the differentiation of T helper 2 (Th2) by inducing separation of RNA binding protein HuR, and so affects the expression of IL-4, IL-5, and IL-13." (PMID 35095993, 2021).
hookworm infection (6 papers, 2011 to 2023). "In this analysis, we also found that hookworm infection among pregnant women was associated with elevated Th1 (IL-1β and IFN-γ) cytokines, as well as IL-5 and CXCL8 in blood collected from the maternal-fetal interface." (PMID 31188820, 2019). "Levels of mRNA encoded by the Th2/Th9 genes IL-4, IL-5, IL-13, IL-9 and GATA-3 appeared unaffected by hookworm infection using this technique." (PMID 22346753, 2012). "Our results show that experimental hookworm infection leads to a strong systemic and mucosal Th2 (IL-4, IL-5, IL-9 and IL-13) and regulatory (IL-10 and TGF-β) response, with some evidence of a Th1 (IFN-γ and IL-2) response." (PMID 22346753, 2012). "In the current study our findings of raised IL-5 and eotaxin support hookworm infection promoting a vaginal eosinophil response which may promote viral establishment and expansion." (PMID 36330509, 2022). "Intriguingly, IL-5 was produced only after hookworm infection in response to QE65." (PMID 21949691, 2011). "A significant increase in IL-5 produced in response to QE65 was seen after hookworm infection (week 20), with a non-significant trend for increased production of IL-13." (PMID 21949691, 2011).
Immunodeficiency (6 papers, 2012 to 2025). Failure of the immune system to protect the body adequately from infection, due to the absence or insufficiency of some component process or substance. "Completely removing eosinophils (as done in some trials with IL-5 antibodies) surprisingly doesn't cause major immunodeficiency in adults, but subtle effects exist (e.g., delayed clearance of some viruses, possible impact on tissue remodeling)." (PMID 40860650, 2025). "al. have studiedimmunological factors including IL-4, IL-5, IL-13 and PGE2 in vaginal discharge in women withRVVC proposing that infected cases had a specificlocal immune deficiency in that area." (PMID 28868834, 2017). "It is believed that in a patient with immunodeficiency due to hematologic disease a trigger-like insect bite, drug, or virus induces cytokine production with an excess of interleukin (IL)-4 and IL-5 and an altered immune response with eosinophil predominance." (PMID 23148793, 2012). "The macrofilaricidal efficacy of both OXF and FBZ was reduced in all tested immunodeficient strains, and treatment efficacy was lowest in strains with more severe immunodeficiency, i.e., IL-4r/IL-5−/− vs. ΔdblGata1 mice, or completely abrogated in Rag2/IL-2rγ−/− mice." (PMID 37440891, 2023). "Some authors have speculated that in patients with an immunodeficiency due to hematologic disease, a trigger, such as a drug or a virus, induces cytokine production with an excess of interleukin (IL)-4 and IL-5, resulting in an altered immune response with eosinophil predominance." (PMID 41375673, 2025).
leprosy (6 papers, 2013 to 2023). Leprosy is a chronic infectious disease affecting primarily the skin and peripheral nervous system. "Early studies of leprosy intradermal cytokine expression determined that leprosy polarity is associated with TH2 cytokines IL4, IL5, IL10 in lepromatous lesions, and TH1 polar cytokines, IFNG, IL2, in tuberculoid lesions." (PMID 25412496, 2014).
migraine (6 papers, 2018 to 2025). "But the levels of IL-6, IL-5, and IL-8 in the migraine group were lower than those in the control group." (PMID 38356891, 2024). "Li Jinhong found that the levels of serum INF-α, IL-2, IL-17, IL-12P70, TNF-α, IL-5, IL-1β, and IL-4 were higher in adult migraine patients than in normal control group, which changed with different stages of the disease." (PMID 38356891, 2024). "Studies on inflammatory mediators in the pathophysiology of headache have shown the main action of IL-5 during migraine episodes." (PMID 29774022, 2018). "IL-5 involvement in pathophysiology of migraine remains unclear." (PMID 38308249, 2024). "In one study in 1998, Munno and colleagues found increased IL-5 levels in patients with migraine compared to healthy controls; however, this was not replicated in other studies, including ours." (PMID 40991059, 2025).
peanut allergy (6 papers, 2014 to 2023). "Proliferative responses to each of these peptides were also associated with the production of the Th2-type cytokine IL-5, suggesting that these peptides contain epitopes relevant to the pathogenesis of peanut allergy." (PMID 25531161, 2014). "In turn, IL-2 may be responsible for the increased plasma IL-5 in our allergic subjects, and successful oral immunotherapy for peanut allergy is associated with a decrease in both IL-5 and IL-2." (PMID 38067164, 2023). "In vitro, allergen-stimulated T cells and T-cell clones generated from patients with peanut allergy produced increased levels of the type 2 cytokines IL-4, IL-5, and IL-13." (PMID 32497050, 2020). "While mainly TH2 cytokines are reduced during OIT, one study of 29 patients (1–16 years) with peanut allergy observed that patients treated with OIT had higher levels of IL-10, IL-5, IFN-γ, and TNF-α from peanut-stimulated PBMCs compared with controls." (PMID 33224138, 2020).
polyposis (6 papers, 2016 to 2024). "Many studies have investigated molecular factors such as interleukin 5, interleukin 10, TGF-B, etc., in polyposis." (PMID 38259689, 2024). "Lymphocyte subpopulations differ between patients without polyposis (TH1 predominant with high levels of interferon-γ) and those with polyposis (TH2 predominant with high IL-5 and IgE levels)." (PMID 26830405, 2016).
prostate carcinoma (6 papers, 2022 to 2025). A carcinoma that arises from epithelial cells of the prostate gland. "In their pilot study with 15 prostate cancer patients, they evaluated the effects of a 24-week HOET on IL-1α, IL-5, IL-6, IL-12, TNF-α, and IFN-γ." (PMID 40498221, 2025). "Furthermore, IFN-γ secreted by natural killer (NK) cells, along with high expression of IFN-γ, TNF-α, IL-5, IL-10, and macrophage inflammatory protein-1 alpha (MIP-1α), has been observed in castration-resistant prostate cancer." (PMID 40430079, 2025).
respiratory infections (6 papers, 2011 to 2024). "In a high-risk cohort, we have previously reported that the ratio of IL-10 and IL-5 was protective against the susceptibility to respiratory infections during infancy and early childhood." (PMID 23724228, 2011).
schizophrenia (6 papers, 2021 to 2025). A major psychotic disorder characterized by abnormalities in the perception or expression of reality. "Compared to EOS, IL-5 demonstrated greater predictiveaccuracy for schizophrenia; however, its diagnostic value as a standalone markerremains limited." (PMID 40926813, 2025). "∙ IL-5 demonstrates greater predictive accuracy for schizophrenia compared to EOS;however, its diagnostic value as a standalone marker remains limited." (PMID 40926813, 2025). "In conclusion, theincrease in EOS observed in schizophrenia patients may be associated withincreased IL-5, and patients with longer disease duration may exhibit higher EOSlevels." (PMID 40926813, 2025). "Research on IL-5 with schizophrenia has so far been limited, and themechanisms underlying its potential role remain unclear." (PMID 40926813, 2025). "Subgroup analyses based on age, gender, and disease severity furtherrevealed that IL-5 levels were significantly elevated in schizophrenia patientscompared to healthy controls across all subgroups, except for those aged >60years." (PMID 40926813, 2025). "After two months of drug treatment, the PANSS scores and IL-5 levels all showedsignificant reductions in first-episode schizophrenia patients." (PMID 40926813, 2025). "In the present study, IL-5 levels in patients with schizophrenia weresignificantly higher than those in healthy individuals, consistent with previousfindings." (PMID 40926813, 2025). "∙ IL-5 levels were significantly elevated in both the first-episode schizophreniagroup and the recurrent/chronic schizophrenia group, whereas eosinophils (EOS) levels wereexclusively elevated in the recurrent/chronic schizophrenia group." (PMID 40926813, 2025). "The first-episode schizophrenia group and the recurrent/chronic schizophrenia group had elevated IL-5 levels relative to healthy controls; however, the increase in EOS levels was specifically observed in the recurrent/chronic schizophrenia group." (PMID 40926813, 2025). "The cytokines produced by Th2 (IL-4, IL-5, and IL-13) were also increased in patients with schizophrenia (P < 0.001; P < 0.001; P = 0.012, respectively)." (PMID 35223927, 2022). "Males with schizophrenia had statistically significantly higher levels of IL-10 (p = 0.017), IL-5 (p = 0.048), and TNF-α (p = 0.025) than did healthy age-matched males." (PMID 36556337, 2022). "Elevated levels of IL-5 in the serum of patients with schizophrenia have been demonstrated, in line with our results." (PMID 36556337, 2022). "IL-5 exhibitedsuperior predictive performance for schizophrenia compared to EOS." (PMID 40926813, 2025). "The difference in IgA levels between blood and mucosa suggeststhat the effect of IL-5 on IgA may mainly be manifested in mucosal sites such asthe intestine in schizophrenia." (PMID 40926813, 2025). "Therefore, this study attempts to establish associations between serum cytokines IL-6, IL-12, IL-5, IL-10 and TGF-β1 changes and the effectiveness of ECT in treatment-resistant schizophrenia patients." (PMID 39595201, 2024). "This suggests that elevated IL-5 levels may persist throughoutthe course of schizophrenia." (PMID 40926813, 2025). "Furthermore, IL-5 exhibits greater predictive accuracy for schizophrenia compared to EOS, suggesting that IL-5 may serve as a valuable biomarker for auxiliary diagnosis and stratification analysis in schizophrenia." (PMID 40926813, 2025). "IL-5, EOS, and IgA levels in healthy individuals and inpatients with first-episode schizophrenia and recurrent/chronic schizophrenia." (PMID 40926813, 2025). "Comparison of PANSS scores, IL-5, EOS and IgA levels infirst-episode schizophrenia patients before and after treatment (n = 57)." (PMID 40926813, 2025). "ROC curve analysis revealed that IL-5 and EOS exhibited area under the curve(AUC values) for schizophrenia of 0.641 and 0.596, respectively, withsensitivities of 52.9% and 86.9%, and specificities of 69.4% and 31.9%." (PMID 40926813, 2025).